HOXD4 (homeobox D4)
Diseases named in the same sentence as HOXD4 in open-access papers:
HOXD4 is named in the same sentence as 31 diseases in open-access papers, as found by Europe PMC text mining. Sharing a sentence is not in itself a finding about the gene and the disease. The quoted sentences say what the papers report.
breast carcinoma (8 papers, 2009 to 2023). "HOXD1, HOXD3, and HOXD4 were transcription factors and have been recognized as oncogenes in many cancers, such as liver cancer, gastric cancer, breast cancer, and as an inhibitor in kidney renal clear cell carcinoma." (PMID 37827698, 2023). "For example, HOXD4 was overexpressed and positively correlated with oncogene-like character in spontaneously derived neoplastic canine mammary carcinoma cell models." (PMID 35317110, 2021). "MiR-10a recognizes a complementary region within the homeobox D4 (HOXD4) promoter and reduces HOXD4 gene expression in breast cancer cells." (PMID 29401683, 2018). "HOXD4 belongs to the homeobox family of genes and we can observe the change of HOXD4 in tumors like colon carcinoma and breast cancer." (PMID 30115812, 2018). "In human breast cancer cells, miR-10a can repress the expression of Hoxd4 by a transcriptional mechanism, thus demonstrating the function of miR-10a in the regulation of human genes." (PMID 23696417, 2013). "miR-10b is found 5′ to Hoxd4 and regulates metastasis and cell migration in human breast cancer cells via suppression of Hoxd10." (PMID 21991333, 2011). "miR-10a, located upstream of Hoxb4, was reported to repress Hoxd4 transcription by targeting its promoter region in human breast cancer cells." (PMID 21991333, 2011).
acute lymphoblastic leukemia (4 papers, 2015 to 2022). Leukemia with an acute onset, characterized by the presence of lymphoblasts in the bone marrow and the peripheral blood. "Among the germline mutations analyzed in the HOX paralogous groups from 4 to 13, the HOXD4 missense mutation was seen in the patients of acute lymphoblastic leukemia (ALL)." (PMID 34617205, 2022). "Germline missense mutation in another HOX transcription factor, HOXD4, was also detected to be associated with an increased risk of childhood acute lymphoblastic leukemia (ALL)." (PMID 31013831, 2019).
gastric cancer (3 papers, 2021 to 2023). A primary or metastatic malignant neoplasm involving the stomach. "Overexpression of HOXD4 is significantly associated with poorer prognosis in patients with gastric cancer (GC), suggesting the potential of HOXD4 as a novel clinical predictive biomarker and drug target." (PMID 36213580, 2022). "For example, HOXD4 may promote proliferation by up-regulating c-Myc and cyclin D1 in gastric cancer cells." (PMID 35317110, 2021). "As reported in breast and gastric cancers, HOXD4 can be negatively regulated by microRNA-10b." (PMID 35317110, 2021).
glioma (3 papers, 2017 to 2024). A benign or malignant brain and spinal cord tumor that arises from glial cells (astrocytes, oligodendrocytes, ependymal cells). "HOXD4 expression was associated with the clinical outcomes of glioma patients, making HOXD4 a promising potential prognostic biomarker for gliomas." (PMID 37865919, 2024). "Meanwhile, expression of HOXD4 was revealed an independent prognostic factor in patients with gliomas." (PMID 29383189, 2017). "Data analysis demonstrated that HOXD4 expression was an independent prognostic factor significantly influencing the survival of patients with gliomas." (PMID 29383189, 2017). "As results was shown, One-way Anova analysis with Bonferroni correction demonstrated that the expression of HOXD4 was remarkably elevated in gliomas than normal brain (p=0.047)." (PMID 29383189, 2017). "The clinicopathological features of the glioma cohort was summarized according to the HOXD4 expression level." (PMID 29383189, 2017). "Univariate analysis demonstrated that group with low HOXD4 expression had a considerably better OS than group of high HOXD4 expression in total glioma patients (Figure 3Ep<0.001) and WHO II (Figure 3Fp<0.001), III (Figure 3Gp=0.012)." (PMID 29383189, 2017). "Univariate and multivariate analysis were conducted to investigate the prognostic role of HOXD4 in glioma patients." (PMID 29383189, 2017). "One-way Anova analysis with Bonferroni correction revealed that staining score of HOXD4 was higher in glioma than normal brain (p=0.021), and also significantly higher in GBM than LGG (p=0.001)." (PMID 29383189, 2017). "In our current study, the expression of HOXD4 in Grade II, III, IV gliomas and normal brain tissue samples was detected by qRT-PCR, indicating that HOXD4 is widely present in glioma tissues." (PMID 29383189, 2017). "Clinicopathological analysis of HOXD4 expression in 453 glioma patients was performed in the current study." (PMID 29383189, 2017). "The expression of HOXD4 in glioma tissues was ladder-like elevated as the pathological grades escalated, which is in accordance with the results of TCGA data analysis." (PMID 29383189, 2017). "In conclusion, the current results demonstrated the expression of HOXD4 was elevated in gliomas and closely correlated with the malignancy of gliomas." (PMID 29383189, 2017). "Kaplan-Meier survival curve was used to demonstrate the relationship between HOXD4 expression and survival times of glioma patients." (PMID 29383189, 2017). "We calculated the average values of the staining scores of HOXD4 expression in normal brain tissues and gliomas." (PMID 29383189, 2017). "Multivariate survival analysis including putative prognostic factors such as KPS, radiation therapy, chemotherapy, resection extent demonstrated that HOXD4 was an independent prognosis factor in glioma patients." (PMID 29383189, 2017). "The expression of HOXD4 was considerably higher in WHO grade III gliomas than Grade II gliomas (p<0.001)." (PMID 29383189, 2017). "High expression of HOXD4 was determined in 178 samples, consisting of 39.29% in all glioma samples while the others were considered as low expression (60.71%)." (PMID 29383189, 2017). "Second, further experiments focused on molecular mechanism of HOXD4 in glioma carcinogenesis and progression was needed in the future." (PMID 29383189, 2017). "Univariate analysis demonstrated that patients age (p<0.001), extent of resection (p=0.012), postoperative radiation therapy (p<0.001), postoperative chemotherapy (p<0.001) and HOXD4 expression (p<0.001) impact the prognosis in total glioma patients." (PMID 29383189, 2017). "patients with high HOXD4 expression had a significant shorter survival than those with low HOXD4 expression in total glioma cohort (p<0.001), WHO Grade II cohort (p=0.003) and Grade III cohort (p<0.001), but not in Grade IV cohort when OS (overall survival) was analyzed (p=0.216)." (PMID 29383189, 2017).
glioma (continued). "HOXD4 may be an important prognostic factor and a potential therapeutic target for glioma in the future." (PMID 29383189, 2017). "Moreover, it was revealed that the expression of HOXD4 have a significant impact on the OS of Grade IV glioma with IDH wild-type and 1p/19q intact according to TCGA data." (PMID 29383189, 2017). "Expression of HOXD4 was closely related to the clinical outcomes of patients with gliomas, and HOXD4 may be a potential prognostic biomarker of gliomas." (PMID 29383189, 2017). "Besides, HOXD4 was up-regulated in glioma tissues compared with normal brain tissues." (PMID 35317110, 2021). "Glioma patients with higher HOXD4 expression showed a significantly shorter survival than those with lower HOXD4 expression, indicating that HOXD4 may be a potential prognostic factor of gliomas." (PMID 35317110, 2021). "However, in the comparison of tumor tissue and normal brain tissue, we found that HOXD4 expression was significantly increased, suggesting that HOXD4 may play a role in the progression of gliomas." (PMID 29383189, 2017). "As the Kaplan-Meier survival curve revealed, in total glioma patients (Figure 3Ap<0.001) and WHO II (Figure 3Bp=0.001), III (Figure 3Cp<0.001), patients with high HOXD4 expression have a significantly shorter OS than those with low HOXD4 expression." (PMID 29383189, 2017). "As IDH has a clear impact to the prognosis of glioma patients, survival analysis of GBM patients with IDH wild-type may be another solution for studying the effects of HOXD4 on clinical outcomes." (PMID 29383189, 2017). "The data demonstrated that and the results demonstrated that HOXD4 was overexpressed in glioma tissues compared to that of normal brain tissues." (PMID 29383189, 2017). "There is no statistical significance between HOXD4 expression and survival time in Grade IV glioma cohort (Figure 3Hp=0.100)." (PMID 29383189, 2017). "However, HOXD4 expression is not a prognostic factor of significance in Grade IV gliomas (Figure 3Dp=0.077)." (PMID 29383189, 2017).
ovarian carcinoma (3 papers, 2021 to 2025). A malignant neoplasm originating from the surface ovarian epithelium. "High HOXD4 expression is associated with poorer prognosis of ovarian cancers and gastric adenocarcinoma." (PMID 37865919, 2024). "Yu and Guo revealed the prognostic significance of HOXD4 in ovarian cancer." (PMID 39858044, 2025).
gastric adenocarcinoma (2 papers, 2023 to 2024). "In gastric adenocarcinoma, highly expressed HOXD4 is associated with positive lymph node metastasis and enhanced proliferation of gastric adenocarcinoma by increasing c-Myc and cyclin D1." (PMID 37827698, 2023). "Upregulation of HOXD4 was markedly correlated with poorer prognosis of gastric adenocarcinoma patients." (PMID 37827698, 2023). "Hui Liu reported that overexpression of HOXD4 could lead to poor clinical outcomes in gastric adenocarcinoma." (PMID 37827698, 2023).
glioblastoma (2 papers, 2020 to 2021). The most malignant astrocytic tumor (WHO grade IV). "Several reports have suggested that high expression of homeotic genes, including HOXA9, HOXA13, mesenchyme HOX2 (MEOX2), and HOXD4 is an indicator of poor prognosis in glioblastoma (GBM) patients." (PMID 34458259, 2021).
ovarian serous carcinoma (2 papers, 2021 to 2022). "HOXD4 protein expression may be associated with poorer prognosis in ovarian serous carcinoma." (PMID 36213580, 2022). "Here we aimed to study the HOXD4 expression in ovarian serous carcinoma (OSC) and determine its clinical significance." (PMID 35317110, 2021).
acute myeloid leukemia (1 paper, 2012). Acute myeloid leukemia (AML) is a group of neoplasms arising from precursor cells committed to the myeloid cell-line differentiation. "For instance, loss of HOXA5 in breast cancer, over-expression of HOXA10 in acute myeloid leukemia (AML), gene mutations of HOXD4 in renal and colon cancer and overexpression of HOXC4 in human bladder cancer have been reported." (PMID 22768238, 2012).
atherosclerosis (1 paper, 2015). A disease characterized by the build-up of fatty material and calcium deposition in the arterial wall resulting in partial or complete occlusion of the arterial lumen. "Methylation level (mean ±SD) at the promoter of HOXD4 gene in paired vascular tissues from twenty one patients with atherosclerosis." (PMID 25856389, 2015). "Although the functional significance of HOXD4 in atherosclerosis remains unclear, a previous study identified differential expression of this gene in the samples of human aorta with varying degrees of atherosclerosis." (PMID 25856389, 2015).
Barrett’s oesophagus (1 paper, 2018). "The 10 other genes were significantly hyper-methylated in Barrett’s oesophagus compared with normal squamous tissue (HOXD4, PTRO and RPIB9 with p<0.01 and the rest of the genes with p<0.05)." (PMID 29084829, 2018).
bladder urothelial carcinoma (1 paper, 2023). "Meanwhile, the association of HOXD1 expression with DFI was analyzed, and the results showed that high expression of HOXD1 induced poor DFI in KICH and PRAD (p < 0.01); HOXD3 in ACC, BLCA (bladder urothelial carcinoma), and PRAD (p < 0.01); HOXD4 in BLCA, ESCA, KICH, PCPG, and PRAD (p < 0.01)." (PMID 37827698, 2023).
chordoma (1 paper, 2023). Chordomas are rare malignant tumors arising from embryonic remnants of the notochord in axial skeleton. "Comparison of chordoma with NP showed DMRs in many cancer-related genes as well as in genomic cluster encoding homeobox domain genes (at HOXD3, HOXD4 and HOX11, HOXA9, HOXA10) that play an important role in both normal differentiation and tumorigenesis." (PMID 37434245, 2023). "Chordoma-specific DMRs were also found in location of homeobox domain genes (e.g. DMRs in HOXA4, HOXA5, HOXD3, HOXD4 MNX1, and NFIX) especially on chromosome 2 at HOXD cluster." (PMID 37434245, 2023).
embryonal carcinoma (1 paper, 2011). A non-seminomatous malignant germ cell tumor characterized by the presence of large germ cells with abundant cytoplasm resembling epithelial cells, geographic necrosis, high mitotic activity, and pseudoglandular and pseudopapillary structures formation. "Here, we show that the expression profiles of Hoxd4 and miR-10b transcripts during neural differentiation of mouse embryonal carcinoma (EC) P19 cells are co-ordinately regulated, suggesting that both Hoxd4 and miR-10b expression is governed by the neural enhancer." (PMID 21991333, 2011).
Ewing sarcoma (1 paper, 2018). A small round cell tumor that lacks morphologic, immunohistochemical, and electron microscopic evidence of neuroectodermal differentiation. "Notably, all but one of these (HOXD4) have previously been implicated in the promotion of cancer, and HOXD11 has specifically been demonstrated to be disease-promoting in Ewing Sarcoma." (PMID 30237855, 2018).
lentivirus infection (1 paper, 2021). Virus diseases caused by the Lentivirus genus. "A2780 cells showed the highest endogenous HOXD4 level, thus were selected for knockdown experiments using specific shRNA by lentivirus infection." (PMID 35317110, 2021).
lung carcinoma (1 paper, 2021). "HOXD4 was reported up-regulated in lung squamous cell carcinoma resulting in more aggressive invasiveness of lung cancer cells." (PMID 34262872, 2021).
prostate carcinoma (1 paper, 2024). A carcinoma that arises from epithelial cells of the prostate gland. "By contrast, GO analysis of the genes upregulated in the BPH-PCa group while downregulated in men with symptomatic BPH were several transcription factors related to prostate cancer, such as NKX3-1 and members of the HOX family like HOXB13, HOXB7, HOXD4, HOXC10 and HOXC8." (PMID 38201640, 2024).
tumor (8 papers, 2017 to 2023). "Our first pan-cancer analyses of HOXD1, HOXD3, and HOXD4 indicate that those factors were differentially expressed between normal and tumor tissues and reveal associations of gene expression with clinical indicators." (PMID 37827698, 2023). "Furthermore, in the KIRC, all HOXD1, HOXD3, and HOXD4 expressions were negatively linked with the tumor stage." (PMID 37827698, 2023). "In varying degrees, HOXD1, HOXD3, and HOXD4 participated in the initiation and progression of the tumor." (PMID 37827698, 2023). "The xenograft growth curves showed that silencing HOXD4 can remarkably suppress tumor growth in vivo." (PMID 35317110, 2021). "Of note, our study initially provided in vivo evidence on the tumor-related role of HOXD4 in OC progression." (PMID 35317110, 2021). "Therefore, In the KIRC, all of HOXD1, HOXD3, and HOXD4 expression was significantly correlated with tumor stage (shown in red square frame)." (PMID 37827698, 2023). "The correlation test demonstrated a significant correlation between HOXD4 with tumor FIGO stage." (PMID 35317110, 2021). "Furthermore, we confirmed the tumor-related role of HOXD4 in OSC by in vitro and in vivo experiments." (PMID 35317110, 2021). "Moreover, higher HOXD4 was correlated with advanced tumor stages and served as an independent unfavorable prognostic factor." (PMID 35317110, 2021). "Moreover, HOXD1, HOXD3, and HOXD4 could be applied to evaluate immune cells’ infiltration in various tumor tissues." (PMID 37827698, 2023). "HOXD1, HOXD3, and HOXD4 are members of the HOXD genes family and are related to tumorigenesis of the tumor." (PMID 37827698, 2023). "Tumor Immune Estimation Resource, Single-Cell Analysis, and gene set enrichment analysis (GSEA) were performed to investigate the special functions and mechanisms of the HOXD1, HOXD3, and HOXD4 in cancers." (PMID 37827698, 2023).
cancer (3 papers, 2018 to 2023). A tumor composed of atypical neoplastic, often pleomorphic cells that invade other tissues. "GSEA was performed to assess the signaling pathways of HOXD1, HOXD3, and HOXD4 that cause their differential expression in each cancer." (PMID 37827698, 2023). "Above all, these results indicated that HOXD1, HOXD3, and HOXD4 expression was significantly enriched with pathways associated with the immune-activation status and progression of cancers." (PMID 37827698, 2023). "Results confirmed that differential expression of HOXD1, HOXD3, and HOXD4 between cancer tissues and normal tissues existed in many types of cancer." (PMID 37827698, 2023). "HOXD4 was positively associated with the B cells, CAF, Endo, monocytes, dendritic, NK, and Tregs cells in most of the cancers and negatively associated with the γ/δT cells in most cancers except UVM, THCA, GBM, ESCA, DLBC cancers." (PMID 37827698, 2023). "Meantime, HOXD1, HOXD3, and HOXD4 co-inhibition was demonstrated in 7 cancers, such as BRCA, COAD, KICH, KIRC, KIRP, READ, TGCT." (PMID 37827698, 2023). "Meantime, the GSEA result showed that HOXD1, HOXD3, and HOXD4 were connected with the immune infiltration in pan-cancer." (PMID 37827698, 2023). "The current study conducted the bioinformatics database to analyze the expression of HOXD1, HOXD3, and HOXD4 in common cancers." (PMID 37827698, 2023). "Whereas, the molecular function of HOXD1, HOXD3, and HOXD4 in tumorigenesis, recurrence, and metastasis of various cancers have still unknown." (PMID 37827698, 2023). "Next, the expression of HOXD4 in various cancers was evaluated in the TCGA database." (PMID 37827698, 2023). "Furthermore, the expression of HOXD1, HOXD3, and HOXD4 remarkably correlated with histological grade was demonstrated in 11 cancer types." (PMID 37827698, 2023). "Meanwhile, HOXD4 was connected with the clinical stage of cancers, including KIRC (p < 0.05)." (PMID 37827698, 2023). "Our findings suggest that HOXD1, HOXD3, and HOXD4 expression will bring different prognostic outcomes, which needs to be further studied for the specific role of HOXD1, HOXD3, and HOXD4 in each cancer." (PMID 37827698, 2023).
infection (1 paper, 2021). The state of being infected such as from the introduction of a foreign agent such as serum, vaccine, antigenic substance or organism. "By using the shRNA infection strategy, our data demonstrated that silencing HOXD4 significantly attenuated the proliferation capacity of OSC cells, which is consistent with its reported role in other malignancies." (PMID 35317110, 2021).
HOXD4 also shares sentences with these, for which no sentence is quoted: anencephaly (1 paper); cervical carcinoma (1); colon carcinoma (1); congenital heart defects (1); leukemia (1); liver cancer (1); lung adenocarcinoma (1); lung squamous cell carcinoma (1); neuroblastoma (1); renal cell carcinoma (1).